GPER1 (G protein-coupled estrogen receptor 1)
Diseases named in the same sentence as GPER1 in open-access papers (continued):
Sharing a sentence is not in itself a finding about the gene and the disease.
acute kidney injury (2 papers, 2014 to 2022). Sudden and sustained deterioration of the kidney function characterized by decreased glomerular filtration rate, increased serum creatinine or oliguria. "In addition, it has been shown that GPER1 signaling elicits protective actions against acute ischemic injuries that involve multiple organ systems; however, the involvement of GPER1 signaling in Cp-induced acute kidney injury (AKI) remains unclear." (PMID 35955435, 2022). "GPER1 knockout did not exacerbate the Cp-induced AKI, as demonstrated by serological, histological, and renal tissue markers of injury, findings that are in agreement with previous reports in an acute kidney injury model." (PMID 35955435, 2022).
age (2 papers, 2023). A temporal measurement of the time period elapsed since an identifiable point in the life cycle of an organism. "As GPER1 activation has been shown to improve cognitive function in a mouse model of AD, the effects of GPER1 on TA-CA1 synaptic efficacy is also likely to have implications for memory and cognitive function in health and in age-related neurodegenerative conditions like AD." (PMID 36709268, 2023).
chronic kidney disease (2 papers, 2023). Impairment of the renal function secondary to chronic kidney damage persisting for three or more months. "Specifically, GPER1 is crucial in preventing TECs from developing into immune-like cells, exacerbating kidney inflammation, and contributing to End-Stage Renal Disease (ESRD) development." (PMID 38086848, 2023).
cutaneous melanoma (2 papers, 2023 to 2024). A primary melanoma arising from atypical melanocytes in the skin. "In contrast to GPER1, which is associated with better outcome and mortality rates of cutaneous melanoma in women, collagen XVII (COL17) appears to be implicated in skin cancer development." (PMID 39252786, 2024). "In our study, we analyzed the expression of G-protein coupled estrogen receptor 1 (GPER1) and the endodomain of collagen XVII (COL17) in relation to clinicopathological factors in primary cutaneous melanomas with known lymph node status in both sexes, using immunohistochemistry." (PMID 39252786, 2024). "Our data indicate that GPER1 and COL17 proteins may be of potential prognostic value in primary cutaneous melanomas." (PMID 39252786, 2024).
endometrial adenocarcinoma (2 papers, 2012 to 2024). "Cytoplasmic GPER1 overexpression was also found in high-grade estrogen receptor- and progesterone receptor-negative endometrial adenocarcinomas in association with myometrial invasion and poor survival." (PMID 39252786, 2024).
goiter (2 papers, 2015 to 2022). Enlargement of the thyroid gland usually caused by lack of iodine in the diet, hyperthyroidism, or thyroid nodules. "Nevertheless our data, although preliminary, suggest that GPER1 abnormal gene and protein expressions could be involved in the pathogenesis of goiter as either a cause or a consequence of it." (PMID 25861267, 2015). "GPER1 protein levels were evaluated in 15 samples of normal thyroid and 13 samples of goiter; normal and goiter samples were obtained from the same patient in 7 cases." (PMID 25861267, 2015). "When comparing GPER1 gene and protein levels in both conditions, gene expression and protein levels were higher in normal thyroid than in goiter, suggesting a role of this receptor in this condition." (PMID 25861267, 2015). "We investigated GPER1 gene and protein expressions in normal thyroid and goiter using reverse transcription quantitative polymerase chain reaction (RT-qPCR) and Western blot, respectively." (PMID 25861267, 2015). "GPER1 mRNA was less expressed in goiter than in normal thyroid with median (P25/P75), respectively, 0.8620 (0.09/4.68) and 9.6085 (0.44/16.12)." (PMID 25861267, 2015). "So, the aim of this study was to evaluate the expression of GPER1 in human normal thyroid and goiter." (PMID 25861267, 2015). "Densitometric scanning of the 38 kDa band showed lower expression of GPER1 protein levels in goiter when compared with normal thyroid (P = 0.002), with median (P25/P75), respectively, 0.3332 (0.09/0.88) and 1.5804 (0.81/2.43)." (PMID 25861267, 2015). "GPER1 mRNA was present in all samples studied; normal and goiter samples were obtained from the same patient in 9 cases." (PMID 25861267, 2015). "In normal thyroid (n = 16) and goiter (n = 19), GPER1 gene was expressed in all samples, while GPER1 protein was expressed in all samples of normal thyroid (n = 15) but in only 72% of goiter samples (n = 13)." (PMID 25861267, 2015). "A clinical study demonstrated that GPER1 expression is lower in goiter specimens than in normal thyroid tissues, suggesting that GPER1 may be involved in the pathogenesis of goiter." (PMID 35162942, 2022). "Further studies are needed to elucidate the role of GPER1 in normal thyroid and goiter." (PMID 25861267, 2015). "As female sexual hormones could be directly involved in the pathogenesis of multinodular goiter, we studied GPER1 gene and protein expression in 35 samples of normal thyroid and goiter." (PMID 25861267, 2015). "GPER1 gene expression was lower in goiter when compared to normal thyroid." (PMID 25861267, 2015). "The pathophysiological implications of the lower GPER1 gene and protein expressions in goiter are unknown." (PMID 25861267, 2015). "All normal thyroid samples expressed GPER1 protein, while it was not expressed in four of the goiter samples (28%)." (PMID 25861267, 2015). "Although there are no studies concerning the functional activity of GPER1 neither in normal thyroid cells nor in goiter, the lower gene and protein expression in goiter suggests a role of this gene in its pathogenesis." (PMID 25861267, 2015).
Impaired glucose tolerance (2 papers, 2019 to 2021). An abnormal resistance to glucose, i.e., a reduction in the ability to maintain glucose levels in the blood stream within normal limits following oral or intravenous administration of glucose. "Additionally, in the global GPER-1 knockout model, systemic effects cannot be excluded, such as increased fat mass, increased blood pressure, and impaired glucose tolerance." (PMID 34490260, 2021).
kidney damage (2 papers, 2019 to 2022). "A protective role of GPER1 has been demonstrated in different models of nephropathies that involve the proximal tubule." (PMID 35955435, 2022). "Recent evidence points to a renal protective potential of GPER1 in nephropathies evoked by salt-induced hypertension and ischemia reperfusion in female rats." (PMID 35955435, 2022). "However, the contribution of aldosterone to GPER1-HO-1 interaction in Cp-induced nephropathy remains to be determined." (PMID 35955435, 2022). "Although various recent studies have suggested that GPER1 signaling elicits protective actions against cardiac, cerebral, renal, hepatic, and intestinal injury induced by ischemia reperfusion, whether GPER1 confers protection against Cp-induced kidney damage is not known." (PMID 35955435, 2022).
lupus (2 papers, 2019 to 2021). "Their study suggested that GPER1 provoked the expression of classic inflammation cytokines tumor necrosis factor α (TNF-α) and monocyte chemoattractant protein-1 (MCP-1) and induced monocytosis in systemic lupus erythematosus (SLE)." (PMID 34239558, 2021).
osteosarcoma (2 papers, 2023 to 2025). A usually aggressive malignant bone-forming mesenchymal neoplasm, predominantly affecting adolescents and young adults. "Furthermore, the activation of GPER1 had also been found to inhibit the migration and invasion of osteosarcoma cells through FBXL5-mediated post-translational downregulation of Snail." (PMID 37921845, 2023).
renal fibrosis (2 papers, 2023). A final common manifestation of a wide variety of chronic kidney diseases characterized by glomerulosclerosis and tubulointerstitial fibrosis. "In UUO-induced renal fibrosis, deficiency in Gper1 also led to enhanced expression of chemokines and proinflammatory cytokines and increased macrophage infiltration." (PMID 38086848, 2023). "Macrophages have attracted great attention in the progression of kidney injury, inflammation, and renal fibrosis, whereas activation of GPER1 exerts anti-inflammatory effects via actions on macrophages." (PMID 38086848, 2023). "This study established a new role for GPER1 agonist G-1 in counteracting renal fibrosis, demonstrating its versatility and therapeutic ability in treating various diseases." (PMID 38086848, 2023). "Overall, this is the first study to demonstrate the effect of GPER1 on macrophage-mediated renal fibrosis via inhibition of M1 and M2 macrophage activation." (PMID 38086848, 2023). "In this study, we aimed to investigate the function of macrophage GPER1 in the UUO-induced renal fibrosis model." (PMID 38086848, 2023). "In this study, we sought to investigate the role of GPER1 in macrophages and its potential effects on renal fibrosis progression and development." (PMID 38086848, 2023). "Altogether, these data revealed that activation of GPER1 significantly attenuated renal fibrosis in the OVX UUO model." (PMID 38086848, 2023). "In conclusion, the current study found that GPER1 plays an essential role in the control of macrophage inflammatory and profibrotic responses in renal fibrosis." (PMID 38086848, 2023). "Taken together, these findings confirmed that GPER1 activation protected the male mice against UUO-induced renal fibrosis." (PMID 38086848, 2023). "Moreover, studies with more specific Cre recombinase models for macrophages and tubule epithelial cells are desirable to clarify the specific roles of GPER1 in different cell types that contribute to the progression of renal fibrosis." (PMID 38086848, 2023). "In addition, female mouse macrophages should be used to unveil the GPER1’s role in the sexual dimorphism in renal fibrosis progression." (PMID 38086848, 2023). "Our previous study also showed that antagonizing GPER1 exacerbated renal fibrosis in the UUO model, but the mechanism remains unknown." (PMID 38086848, 2023). "In contrast to early studies indicating that GPER1 activation was only involved in M1 macrophage polarization derived from multiple studies, our data suggested that activating GPER1 inhibited M2 macrophage polarization, leading to ameliorated renal fibrosis." (PMID 38086848, 2023). "Conversely, Gper1 deletion in male UUO mice accelerated renal fibrosis and increased inflammation." (PMID 38086848, 2023). "However, the precise role of GPER1 in macrophage-mediated renal fibrosis is unknown." (PMID 38086848, 2023).
Barrett esophagus (1 paper, 2023). Esophageal lesion lined with columnar metaplastic epithelium which is flat or villiform. "The results showed that GPER1 was over-expressed in esophageal pathological tissues in five analyses, of which three were affiliated with Barrett’s esophagus (p < 0.05), one with EAC, and one with ESCC." (PMID 37762356, 2023). "Combining the information on GPER1 RNA expression from the Oncomine database in Barrett’s esophagus, we proposed that GPER1 might be correlated with the pathogenic initiation of EAC." (PMID 37762356, 2023). "However, in the subgroup of EAC and its precancerous lesion, Barrett’s esophagus, overexpression of GPER1 RNA was increased when compared with the normal tissues." (PMID 37762356, 2023). "Whether the high expression of GPER1 in Barrett’s esophagus contributes to the transfer of precancerous lesions to malignancy is not currently well known." (PMID 37762356, 2023). "The results showed that three samples of Barrett’s esophagus, one of EAC, and one of ESCC showed overexpression of GPER1 RNA." (PMID 37762356, 2023).
brain injury (1 paper, 2025). Acute and chronic (see also brain INJURIES, CHRONIC) injuries to the brain, including the cerebral hemispheres, CEREBELLUM, and brain STEM. "Gper1 inhibition exacerbates TBI-induced neurological and behavioral impairments, which suggests that Gper1 may be a potential therapeutic target for mitigating TBI-associated brain injury." (PMID 40605012, 2025).
cardiomyopathy (1 paper, 2024). A disease of the heart muscle or myocardium proper. "We consider the regulation of Pip4k2c, Ehmt2, Gper1, Dicer 1, Cul4b, Fyco1, Gn3l and TNNT2 in the context of doxorubicin-induced cardiomyopathy as particularly relevant." (PMID 39285385, 2024).
cerebral aneurysm (1 paper, 2013). "This human cerebral vascular endothelial cell model presents implications of estrogen signalling through ERβ and GPER1 for cerebral aneurysm pathogenesis in menopausal and postmenopausal women." (PMID 24319683, 2013).
cervical neoplasms (1 paper, 2023). "GPER1 has been localized in the cytoplasm and nucleus of cervical neoplasms and at the cell membrane, particularly in the area of invasion fronts." (PMID 37762008, 2023).
channelopathies (1 paper, 2023). "As there is growing appreciation for the importance of ion channel membrane trafficking as the basis for many channelopathies, the mechanisms linking GPER1 to HSP90 should be the focus of further studies." (PMID 36085551, 2023).
colorectal adenoma (1 paper, 2023). An adenoma that arises from the colon or rectum. "Tumor suppressor functions for GPER1 came from studies that showed decreased GPER1 expression levels in CRC patients and colorectal adenoma tissues, which correlated with increased tumor progression, lymph node metastasis, and decreased survival rates." (PMID 36384894, 2023).
granulosa cell tumor (1 paper, 2020). A slow-growing, malignant tumor, characterize by the presence of granulosa-like cells and Call-Exner bodies, that is almost always found in the ovary. "Along the same line, it was also reported that α-E through GPER1 could inhibit the spreading of granulosa cell tumors." (PMID 33240808, 2020).
Hernia (1 paper, 2025). "The ESR2- and GPER1-selective antagonists PHTPP and G-15, respectively, exhibited no discernible effects on hernia size compared with placebo treatment." (PMID 39903526, 2025).
immune deficiency (1 paper, 2019). "Immune deficiency may be related to several genes, especially Platelet-derived growth factor alpha (PDGFalpha), caspase recruitment domain 11 (CARD11), N-acetylglucosaminyltransferase lunatic fringe (LFNG), MafK, and G protein-coupled estrogen receptor 1 (GPER-1)." (PMID 31474980, 2019).
inflammatory skin disease (1 paper, 2026). Inflammatory skin disorders covers a broad category that includes many conditions ranging in severity, from mild itching to grave medical health complications These disorders are common in people of all ages and races. "Together, our results identify GPER1 as a negative regulator of keratinocyte hyperproliferation and skin inflammation, suggesting that modulation of this pathway may represent a therapeutic strategy for hyperproliferative inflammatory skin diseases such as psoriasis." (PMID 41862447, 2026).
laryngeal squamous cell carcinoma (1 paper, 2018). A squamous cell carcinoma that arises from the larynx. "This activity could be mediated by ERs or GPER1 (G protein-coupled estrogen receptor 1), which was shown to trigger proliferation and migration in laryngeal squamous cell carcinoma (LaSCC) via Interleukin-6(IL-6) and signal transducer and activator of transcription 3 (STAT3)." (PMID 29498642, 2018).
lipid metabolism disorders (1 paper, 2024). "Recently, we reported that activation of GPER1 mediates the estrogenic effect of dehydroepiandrosterone in the prevention of lipid metabolism disorders and inflammation in female mice." (PMID 38246352, 2024).
Miscarriage (1 paper, 2022). A pregnancy that ends at a stage in which the fetus is incapable of surviving on its own, defined as the spontaneous loss of a fetus before the 22th week of pregnancy. "Moreover, the identification of GPER-1 polymorphisms and evidence that variants of GPER may result in miscarriage during pregnancy suggest that GPER plays an important role in fetal development." (PMID 35788105, 2022).
oral squamous cell carcinoma (1 paper, 2023). "Correspondingly, inhibiting GPER1 resulted in decreased proliferation in experiments involving oral squamous cell carcinoma." (PMID 37762008, 2023).
plasma cell dyscrasias (1 paper, 2023). "In this study, for the first time, we investigated the expression pattern of GPER1 in plasma cell dyscrasias, and the functional sequelae underpinning its selective activation using in vitro and in vivo models of MM, a still incurable plasma cell malignancy." (PMID 37759449, 2023). "Firstly, we interrogated the transcriptome profiles of four GEO datasets to analyze the expression level of GPER1 in different subgroups of plasma cell dyscrasias patients and in normal controls." (PMID 37759449, 2023).
psoriasis (1 paper, 2026). An autoimmune condition characterized by red, well-delineated plaques with silvery scales that are usually on the extensor surfaces and scalp. "Here, we show that GPER1 signaling is downregulated in lesional skin of psoriasis patients and negatively correlates with both inflammation markers and KC proliferation." (PMID 41862447, 2026).
Sciatica (1 paper, 2021). Pain in the lower back and hip radiating in the distribution of the sciatic nerve. "The roles of SLC8A1, RBM20, GPER1, IL27, SOCS1, and GRTP1-AS1 in sciatica or in relieving sciatica are currently unknown." (PMID 33573686, 2021).
steatosis (1 paper, 2026). Increased lipid within the cytoplasm of cells. "The function of GPER1 was validated both in vitro (using a free fatty acid-induced hepatocyte steatosis model treated with the GPER1 agonist G1 or antagonist G15) and in vivo, with assessments of lipid metabolism-related genes, reactive oxygen species, and apoptosis." (PMID 41929249, 2026).
tauopathy (1 paper, 2024). Neurodegenerative disorders involving deposition of abnormal tau protein isoforms (tau proteins) in neurons and glial cells in the brain. "As abnormal tauopathy is initiated by hyperphosphorylation of tau, one hypothesis was that activation of GPER1 is transduced intracellularly by activation of these kinases that ends in hyperphosphorylation of tau and production of tau tangles." (PMID 38750228, 2024).
Ureteral obstruction (1 paper, 2023). Obstruction of the flow of urine through the ureter. "Compared to vehicle-treated ovariectomized (OVX) female and male unilateral ureteral obstruction (UUO) models, we observed that G-1 (GPER1 agonist)-treated OVX female and male UUO mice had fewer renal fibrotic lesions and less M1 and M2 macrophage infiltration in the kidney tissues." (PMID 38086848, 2023).
vasculitis (1 paper, 2019). "Thus, a lack of GPER1 may prevent the regulation of TLR4 expression and may facilitate the development of vasculitis." (PMID 31474980, 2019).